DIRAS3 (DIRAS family GTPase 3)
Diseases named in the same sentence as DIRAS3 in open-access papers (continued):
Sharing a sentence is not in itself a finding about the gene and the disease.
tumor (51 papers, 2007 to 2026). "DIRAS3 is an imprinted tumor suppressor gene that encodes a 26 kD GTPase with homology to RAS that inhibits cancer cell proliferation and motility." (PMID 31003488, 2019). "It was reported that BMI1 or ARHI (DIRAS3) could induce autophagy-mediated necroptosis and necroptosis could augment tumor-associated macrophages M1 polarization and autophagy through other pathways." (PMID 36357839, 2022). "SERPINA1, MAP1LC3A, DIRAS3 were down-regulated in a high risk group and up-regulated in a low risk group, which were potentially tumor suppressor genes; HSPA8, HSPB8 were up-regulated in a high risk group and down-regulated in a low risk group, which were probably promoting oncogenes." (PMID 34876005, 2021). "While it is possible that DIRAS3 expressing autophagic cells have been selected during primary treatment, the small fibrotic tumor nodules found on the peritoneal surface have few tumor associated vessels and it is likely that cancer cells are nutrient deprived." (PMID 31052266, 2019). "In conclusion, our findings reveal a complex interaction between DIRAS3, autophagy, and the tumor microenvironment, particularly the influence of fibronectin in modulating these processes." (PMID 40862729, 2025). "The identification of ATG3, STK25, and DIRAS3 aligns with prior research implicating autophagy and tumor suppression mechanisms in CRC development." (PMID 41463182, 2025). "Re-expression of DIRAS3 and treatment with defactinib produced tumor regression in xenograft models." (PMID 40862729, 2025). "Treatment of dormant DIRAS3-expressing xenografts with chloroquine, an autophagy inhibitor, reduced tumor growth when DIRAS3 was subsequently reduced." (PMID 40862729, 2025). "DIRAS3 is a tumour suppressor gene that plays a role in cell proliferation, apoptosis, and tumour development." (PMID 38203733, 2024). "Existing evidence indicates that DIRAS3 is capable of inhibiting tumor growth in various cancers, yet its role and mechanism in regard to NSCLC remains elusive." (PMID 35170376, 2022). "In summary, the current study suggests that up-regulation of DIRAS3 in NSCLC inhibits tumor proliferation and invasiveness by suppressing the RAS/ERK pathway." (PMID 35170376, 2022). "The GTP-binding protein Di-Ras3 (DIRAS3) has been established as a maternally imprinted tumor suppressor gene." (PMID 35170376, 2022). "Transcription of ESR1 gene is subjected to inhibitory autoregulation that was predicted to involve a network consisting of a multifunctional tumour suppressor gene DIRAS3, TGFB1, and transferrin receptor TFRC." (PMID 35218417, 2022). "In this model, inhibition of DIRAS3-induced autophagy by chloroquine (a lysosomal autophagy inhibitor) reduced tumor growth, further underscoring the importance of autophagic activity to DIRAS3-related dormancy." (PMID 33816262, 2021). "Downregulated tumour suppressors DIRAS3, DLEC1 and PEG3 (all, P < 0.001) were frequently observed in the immune group." (PMID 33522069, 2021). "DIRAS3 re-expression inhibits cancer cell growth, slows motility, regulates autophagy and sustains tumor dormancy." (PMID 31003488, 2019). "In this model, upregulation of DIRAS3 arrests cancer cell growth, prevents angiogenesis, and induces both autophagy and tumor dormancy." (PMID 31052266, 2019). "DIRAS3 protein as an imprinted tumor suppressor shows normal expression level in breast epithelial cells, whereas is under-expressed in more than 70% of BCs." (PMID 30975222, 2019). "Distinct subgroup of the Ras family member 3 (DIRAS3), also called Aplasia Ras homolog member I, is a tumor suppressor gene that induces autophagy in several cancer cell lines." (PMID 30043279, 2018).
tumor (continued). "Our study revealed that DIRAS3 overexpression inhibits tumor migration and invasion by up-regulating MIIP in GC cells." (PMID 30043279, 2018). "The tumor suppressor ARHI (DIRAS3) is a potent inducer of autophagy and its expression results in necroptotic cell death in vitro and tumor dormancy in vivo." (PMID 27784287, 2016). "DIRAS3, also known as ARHI, is a maternally imprinted member of the ras superfamily and is considered to be a tumor suppressor gene." (PMID 26568774, 2015). "DIRAS3, also known as A ras homologue member 1 (ARHI) is a maternally imprinted human tumor suppressor gene that encodes a small G protein with 50–60% aminoacide homology to Rap and Ras." (PMID 24747418, 2014). "Crucially, autophagy that can be regulated by DIRAS3 is mechanistically shown to contribute to tumor immune evasion via the lysosomal degradation of MHC class I molecules, thereby reducing the antigen presentation efficiency and impairing CD8+ cytotoxic T-lymphocyte (CTL)-mediated tumor elimination." (PMID 40649981, 2025). "DIRAS3 is a member of the Ras super-family that is an imprinted tumor suppressor gene." (PMID 39131380, 2024). "In addition, over-expression of DIRAS3 attenuated the tumor growth and reduced the number of lung tumor nodules." (PMID 35170376, 2022). "There is a plethora of evidence suggestive of the inhibitory role conferred by DIRAS3 on tumor growth of various cancers, however, but its potential role and mechanism in NSCLC remain to be unknown." (PMID 35170376, 2022). "In addition to inducing autophagy, DIRAS3 can prevent tumor outgrowth and block angiogenesis, inducing dormancy." (PMID 31003488, 2019). "Loss of imprinted tumor suppressor function for NDN, DIRAS3 and PEG3 might permit growth of cancer cells in culture." (PMID 26689988, 2016). "In this context, GNG12-AS1 may have a tumour-suppressor function in addition to a role in modulating the expression levels of DIRAS3." (PMID 26832224, 2016). "Furthermore, DNA methylation changes differed for cg06191076 within the promoter region of the DIRAS3 gene (also known as ARHI), a suggested tumor suppressor gene and member of the ras superfamily." (PMID 26568774, 2015). "Therefore, silencing the expression of DIRAS3 may demonstrate an inhibitory effect on LGG metastasis accompanied by a long-lasting tumor suppression effect theoretically." (PMID 35923699, 2022). "In addition, we found that SP1 and vascular endothelial growth factors (VEGF) were decreased in DIRAS3-BGC-823 cells, suggesting that DIRAS3 expression may inhibit tumor growth by inhibiting angiogenesis." (PMID 30043279, 2018).
tumor (continued). "Whether or not this is dependent upon selection of a subset of pre-existing DIRAS3 expressing/autophagy positive cancer cells in the primary tumor or an adaptive phenotype that is conferred by a nutrient deprived, poorly vascularized tumor microenvironment remains to be elucidated." (PMID 31052266, 2019). "Distinct subgroup of the Ras family member 3 (DIRAS3), also known as Aplasia Ras homolog member I (ARHI), is a tumor suppressor gene that is involved in tumor development and autophagy." (PMID 30043279, 2018). "Overexpression of DIRAS3 in BGC-823 cells elevated autophagy levels in subcutaneous xenograft and inhibited tumor growth in mice; the hematogenous liver and lung metastasis of cancer cells were also suppressed." (PMID 30043279, 2018). "ARHI (DIRAS3), a maternally imprinted gene, has been studied in depth and found to mediate cell growth, motility, autophagy and tumor dormancy." (PMID 26689988, 2016). "DIRAS3 (also known as ARHI and NOEY2) is a Ras-related imprinted tumour suppressor involved in the inhibition of growth, motility and invasion via several signalling pathways including RAS/MAPK, STAT3 and PI3K32." (PMID 26832224, 2016). "On the protein level, we validated these hub genes expressions of normal tissues and tumor tissues through the HPA database.HSPA8 and HSPB8 expressed higher in tumor tissues than that in normal tissues, while SERPINA1 and DIRAS3 expressed higher in normal tissues against tumor tissues." (PMID 34876005, 2021). "Re-expression of DIRAS3 blocks mutant K-RasG12V and H-RasG12V -induced transformation of 3T3 and MCF-7 cells, prevents cancer cell growth, inhibits motility, induces autophagy and establishes tumor dormancy in xenografts." (PMID 31052266, 2019). "However, whether DIRAS3 re-expression can suppress tumor growth in HNSCC has not yet been studied." (PMID 33038921, 2020).
cancer (38 papers, 2007 to 2025). A tumor composed of atypical neoplastic, often pleomorphic cells that invade other tissues. "The encoded protein, DIRAS3, plays role in autophagy in certain cancer cells by regulating the autophagosome initiation complex." (PMID 35923699, 2022). "Aberrant DNA methylation or expression of several HOX genes, NODAL and DIRAS3 have been implicated in the etiology of cancer." (PMID 26568774, 2015). "Downregulation of DIRAS3 expression has been described for several forms of cancer and has been specifically associated with progression and invasive behavior of neoplastic cells." (PMID 26568774, 2015). "ARHI, also known as DIRAS3, is a maternally imprinted tumor suppressor gene encoding a 26 kDa GTPase with 55%–62% homology to Ras and Rap, which inhibits cancer cell growth, motility, and invasion." (PMID 22481926, 2012). "Further piquing our interest, a number of prior studies have suggested that DIRAS3 expression is negatively associated with cell survival of cancers, such that its expression could potentially restrict proliferation, foci formation, as well as invasiveness in culture." (PMID 35170376, 2022). "We found that FN prevents DIRAS3-induced autophagic cancer cell death by weakening DIRAS3-mediated inhibition of p-FAK and p-AKT." (PMID 40862729, 2025). "Our studies on tissues from patients with benign and malignant thyroid lesions showed a significant contribution of the BRAF V600E mutation and changes in the expression of RASSF1A, DIRAS3, and AKAP9 genes in developing this type of cancer." (PMID 38203733, 2024). "DIRAS3 was also proven to interact directly with Ras-related proteins, arresting the growth and transformation of cancer cells." (PMID 35173535, 2022). "Eventually, low expression of target genes DCTN6 and DIRAS3 enhance cancer cell proliferation and cell survival rate, and accelerate cancer cell invasion." (PMID 35164166, 2022). "A role for RAS dimerization in the aberrant activation of the RAS-ERK pathway, and the resulting tumorigenesis, has been revealed by the overexpression of DIRAS3 in cancer cells." (PMID 34680951, 2021). "Expressing DIRAS3 in xenograft leads to dormant cancer cells, whereas in cell culture, autophagy induction through DIRAS3 leads to cell death." (PMID 34829881, 2021). "The inhibition of autophagy through chloroquine (CQ) treatment leads to a reduced regrowth of these dormant cells in the mouse model, indicating that DIRAS3-induced autophagy is critical for the survival of dormant cancer cells." (PMID 34829881, 2021). "Our results suggest that amino acid or serum deprivation can induce DIRAS3 regulated autophagy, consistent with adaptation of persistent, drug resistant cancer cells to nutrient poor conditions." (PMID 31052266, 2019). "Like DIRAS3, NODAL has been recognized for its role in cancer progression, with abundant expression of NODAL associated with cellular migration, invasion, and metastatic behavior." (PMID 26568774, 2015). "Re-expression of DIRAS3 in cancer cells robustly induced autophagy." (PMID 33816262, 2021). "Interestingly, although DIRAS3 expression resulted in the apoptotic death of cancer cells in culture, it promoted a dormancy-like state in vivo." (PMID 33816262, 2021). "DIRAS3-induced autophagic cancer cell death could be one mechanism that maintains the balance of cancer cell proliferation and cancer cell death, resulting in the ‘dormant’ phenotype." (PMID 31052266, 2019). "Our studies demonstrate that DIRAS3 mediates autophagy induced by nutrient deprivation, and could be a critical mechanism by which persistent, drug resistant cancer cells adapt to nutrient poor conditions." (PMID 31052266, 2019).
cancer (continued). "These previous studies suggest that DIRAS3 expression is negatively correlated with cancer cell survival and that its expression might inhibit proliferation, foci formation, and invasiveness in culture." (PMID 30043279, 2018). "In addition, several of the promoter-hypermethylated genes were associated with the development of human cancers and these include GIPC2, DIRAS3, TYSPL6, EDNRB, FYN, GDNF, RASSF1, and RASSF2." (PMID 21962230, 2011). "DIRAS3 plays a crucial role in inhibiting RAS/MAPK signaling, which is often dysregulated in many cancers." (PMID 41463182, 2025). "The exact mechanisms behind the dysregulation of DIRAS3 in different cancers, including thyroid, are not fully understood." (PMID 38203733, 2024). "Moreover, with the low expression of TF RBMX, it could upregulate miRNA MIR222 for the purpose of downregulating the downstream target genes DIRAS3 and DCTN6, enhancing cancer cell proliferation, cell survival rate, and inducing invasion." (PMID 35164166, 2022). "Interestingly, if autophagy was inhibited functionally by chloroquine treatment while DIRAS3 expression was upregulated, tumors failed to grow upon downregulation of DIRAS3, suggesting a role for autophagy in supporting survival of dormant cancer cells." (PMID 31003488, 2019). "DIRAS3 is the first endogenous, non-RAS protein to heterodimerize with RAS, disrupt RAS clustering, block RAS signaling, and inhibit cancer cell growth." (PMID 40649981, 2025).
infection (2 papers, 2015 to 2020). The state of being infected such as from the introduction of a foreign agent such as serum, vaccine, antigenic substance or organism.
DIRAS3 also shares sentences with these, for which no sentence is quoted: breast tumor (2 papers); metastatic disease (2); Obesity (2); cervical cancer (1); colon cancer (1); follicular adenoma (1); genetic disorder (1); graft versus host disease (1); Optic neuropathy (1); papillary thyroid cancer (1); renal carcinoma (1); sterility (1); Vertigo (1).